CAV1 (caveolin 1)
Diseases named in the same sentence as CAV1 in open-access papers (continued):
Sharing a sentence is not in itself a finding about the gene and the disease.
Sepsis (continued). "Previous study using LPS–induced sepsis model showed that Cav–1 was able to regulate eNOS–derived NO production and inhibited NF–κB activation and expression of pro–inflammatory proteins, iNOS and ICAM–1 in a mouse model of LPS–induced lung injury." (PMID 35911737, 2022). "Caveolin-1 iscritical for enhancing the innate immune response, which contributes to survivalduring LPS-induced sepsis." (PMID 32187326, 2020). "Depletion of either TLR9 or Cav-1 largely eliminates the neutrophil-mediated InP effect in sepsis models in vitro and in vivo." (PMID 31534550, 2019). "Further, examination of clinical samples from patients with sepsis showed that clinical outcomes and likelihood of recovery are closely correlated with mTLR9 and Cav-1 expression in circulating neutrophils." (PMID 31534550, 2019). "Because InP promotes the translocation of TLR9 to the cell membrane and because TLR9 is associated with Cav-1, we reasoned that Cav-1 is likely to be essential for the TLR9-mediated protective effect during sepsis." (PMID 31534550, 2019). "A possible explanation is that sepsis would interfere with the normal function of Cav-1 and would occur via sepsis-induced oxidative stress, since free radicals directly affect the caveolae structure." (PMID 31148948, 2019). "In vitro treatment of EPCs with a low dose of mixed proinflammatory factors is to mimic the early stage of sepsis (T3-T4) in which Cav-1 expression in EPCs was upregulated and angiogenic capacity was enhanced compared to T1." (PMID 31148948, 2019). "We have demonstrated that Cav-1 and Cav-2 play important and antagonistic roles in the outcome of sepsis induced by LPS in mice." (PMID 29250058, 2017). "Cav-1−/− and Cav-2−/− mice helped to elucidate the role of caveolins in the inflammatory response in vivo, particularly during sepsis." (PMID 29250058, 2017). "Studies have also reported that Cav-1 protects against sepsis by modulating the inflammatory response, alleviating bacterial burden, and suppressing thymocyte apoptosis." (PMID 25756273, 2015). "Cav-1 deletion supressed macrophage phagocytosis with impaired bacterial clearance in murine models of sepsis, leading to increased mortality." (PMID 23894397, 2013). "While Cav-1 plays a role in sepsis by regulating membrane traffic and intracellular signaling pathways, Cav-1 directly modulates ROS production via NADPH oxidase, as NADPH oxidase subunits have been shown to localize within Cav-1-containing caveolae across various cell types." (PMID 40041164, 2025). "A recent paper provides a comprehensive review of Cav-1’s role in sepsis." (PMID 40041164, 2025). "Previous studies have indicated that TLR9 has a detrimental effect on cardiac function during sepsis, and another study reported that TLR9/Caveolin-1 signaling may help predict treatment outcomes in sepsis patients." (PMID 39861004, 2025). "Salidroside may improve lung function in mice with acute lung injury from CLP-induced sepsis by inhibiting caveolin-1 and TLR/NF-kappa B pathways in vivo inhibiting caveolin-1 and TLR/NF-kappa B pathways in vivo." (PMID 38567353, 2024). "Furthermore, protein C administration during sepsis resulted in decreased levels of inflammatory cytokines, apoptosis and Cav–1." (PMID 35911737, 2022). "Thus, the expression of Cav–1 by different mechanisms can modify lung function at a cellular and systemic level, making Cav–1 a promising candidate in the fight against sepsis and mortality." (PMID 35911737, 2022). "The Cav1–eNOS interaction during sepsis may represent a new therapeutic approach for the treatment of acute lung injury." (PMID 35911737, 2022). "Cav–1 had a significant protective role in sepsis and endotoxemia." (PMID 35911737, 2022). "The differential regulatory roles of Cav–1 for different receptors and intracellular signal transduction pathways demonstrate the complex involvement of Cav–1 in the development of diseases, making Cav–1 a candidate in the battle against sepsis–induced mortality." (PMID 35911737, 2022).
Sepsis (continued). "Furthermore, according to another previous study, Dex can up‐regulate the expression of Cav‐1 in lung tissues of sepsis rats and help to inhibit inflammation." (PMID 34114328, 2021). "D+L group could significantly increase the level of Cav-1 protein and decrease the level of TLR-4 and NLRP3 protein in liver tissue caused by sepsis." (PMID 33558888, 2021). "The underlying mechanism is that dexmetomidine may up-regulate the expression of Cav-1 down-regulated by sepsis, which may conduce to the suppression of TLR-4/NLRP3-mediated signaling pathway, at least in part." (PMID 33558888, 2021). "The findings from a mouse model of sepsis indicated that CAV1 is an important protective modulator of sepsis, as CAV1 may regulate inflammation and reduce the bacterial burden." (PMID 33966642, 2021). "Based on our previous study, we used a low dose of mixed proinflammatory factors that may simulate the early stage of sepsis in vitro, to induce Cav-1 expression in EPCs." (PMID 31148948, 2019). "Our finding suggests that TLR9/Cav-1 signaling might be useful for predicting therapeutic outcomes in patients with sepsis." (PMID 31534550, 2019). "However, in the early stage of sepsis, both Cav-1 and eNOS were upregulated in vivo and the number and function of EPCs increased accordingly." (PMID 31148948, 2019). "During the progression of MODS, changes of Cav-1 expression in EPCs were generally consistent with functional changes, with a rapid increase after hemorrhagic shock, and maintained at high level in the early phase of sepsis (24 hours after endotoxemia; T3)." (PMID 31148948, 2019). "Thus far, we showed that TLR9 and Cav-1 interaction is critical for the protective effect of InP against sepsis, but it was unclear how these molecules interact with one another." (PMID 31534550, 2019). "Using a well-established sepsis animal model, Cav-1 knockout mice showed prolonged and uncontrolled cytokine generation and increased bacterial burden, suggesting that Cav-1 may be a critical protective modulator in animal sepsis." (PMID 25756273, 2015). "However, how Cav-1 is involved in sepsis remains unclear, and the precise mechanisms need to be further investigated." (PMID 35911737, 2022). "The functions of Cav–1 during cell regulation may have important implications during sepsis." (PMID 35911737, 2022). "Therefore, sepsis-induced oxidative stress may alter caveolin-1 function and thus eNOS regulation, leading to uncontrolled activation." (PMID 31148948, 2019). "A recent study demonstrated that pravastatin ameliorates sepsis-induced ALI, improves the alveolar endothelial barrier, and inhibits apoptosis in pulmonary parenchyma through regulating the caveolin-1/eNOS signaling pathway." (PMID 35269738, 2022). "Cav–1 phosphorylation was required for interaction with TLR4 and activation of TLR4–MyD88 signaling and sepsis–induced lung inflammation." (PMID 35911737, 2022). "Inhibition of Cav–1 Tyr14 phosphorylation and the resulting inactivation of TLR4 signaling in pulmonary vascular endothelial cells represented a strategy to prevent sepsis–induced lung inflammation and injury." (PMID 35911737, 2022). "Our results also suggest that the anti-inflammatory role of CAV1 in bacterial- and CLP-induced sepsis is most likely dependent on its dysregulation of cytokine production in myeloid cells." (PMID 28593998, 2017). "Other studies showed that Cav1 coordinated and coupled with Notch1/HES1 in the liver tissue of LPS–induced septic mice, which promoted the production of IL–10 in macrophages, leading to inhibition of inflammation in a model of sepsis." (PMID 35911737, 2022). "However, Cav-1 expression and EPC function begin to decline when sepsis continues to progress." (PMID 31148948, 2019).
Sepsis (continued). "As Cav-2 is not expressed in Cav-1−/− mice, we conclude that the observed effects in Cav-2−/− mice are not only due to the absence of Cav-2, supporting the idea that the balance of Cav-1 and Cav-2 activities is important for the expression of iNOS and the progress to sepsis." (PMID 29250058, 2017). "Since Cav-2 is almost completely absent in Cav-1 KO mice, the authors concluded that not just the absence of Cav-2, but also the balance between Cav-1 and -2 is important for iNOS expression and ultimately for sepsis outcome." (PMID 22229094, 2011). "However, the regulatory mechanisms of autophagic flux by Cav–1 during sepsis are not yet known." (PMID 35911737, 2022).
lymph node metastasis (21 papers, 2002 to 2024). "For instance, in renal cell carcinoma, elevated CAV1 levels are associated with a high tumor grade, lymph node metastasis, and decreased survival rates." (PMID 39596307, 2024). "High membranous CAV1 expression was significantly associated with age (p < 0.01), lymph node metastasis (p < 0.01), clinical stage (p < 0.01), and regional recurrence (p < 0.01)." (PMID 37047005, 2023). "Expression of CAV1 in tumor-associated stroma and corresponding lymph node metastasis associated stroma (n = 32) showed concordance in 53.1% of the cases (n = 17)." (PMID 29850392, 2018). "Stromal Cav-1 loss was also associated with lymph node metastasis (P = 0.014) and distant metastasis (P = 0.027)." (PMID 24949874, 2014). "Further studies to validate CTSB as a prognostic marker in IBC and delineate the mechanisms by which the association of CTSB with cav-1 is involved in lymph node metastasis in IBC patients are in progress." (PMID 21199580, 2011). "In lung SCC with lymph node metastasis, Cav-1 is mainly detected in stage III, and Cav-1-positive patients show a lower 5-year survival rate compared to the Cav-1-negative patients." (PMID 31991790, 2020). "When the stromal expression in matched primary tumors and lymph node metastases was compared, both CAV1 and CAV2 expressions were frequently found lost in the corresponding stroma of the lymph node metastasis (40.6%, p = 0.003 and 38.4%, p = 0.001, resp)." (PMID 29850392, 2018). "Loss of stromal Cav-1 is closely correlated with advanced TNM stage, lymph node metastasis, distant metastasis, and poor prognosis." (PMID 24949874, 2014). "Stromal Cav-1 loss was associated with TNM stage (P = 0.018), lymph node metastasis (P = 0.014), distant metastasis (P = 0.027), and HER-2/neu amplification (P = 0.007)." (PMID 24949874, 2014). "Upon univariate analysis with Cox's proportional hazards model, lymph node metastasis (P=0.0007), tumour diameter (P=0.0027), positive surgical margin (P=0.0014) and caveolin-1 immunopositivity (P=0.0011) were all positively correlated with poor prognosis." (PMID 12402154, 2002). "In oesophageal squamous cell carcinoma, expression of caveolin-1 was positively correlated with histopathologic stage, lymph node metastasis and distant metastasis." (PMID 12402154, 2002). "The CAV1 expression in stromal cells was also analyzed in 39 lymph node metastases samples." (PMID 29850392, 2018). "Associations between Cav-1 expression and clinicopathological features, including well-known prognostic factors such as pathologic TNM stage, lymph node metastasis, lymphovascular invasion, degree of differentiation, and Lauren classification, were also explored." (PMID 28828003, 2017). "Although Cav-1 levels in lung tumor tissues are significantly lower than in tumor-free lung tissues, the expression of Cav-1 in lung tumor tissues is markedly higher in patients with lymph node metastasis and advanced tumor stage." (PMID 25202343, 2014). "In addition, the upregulation of Cav-1 expression was found to significantly correlate with advanced pTNM stage (P=0.027) and lymph node metastasis (P=0.018)." (PMID 25202343, 2014). "PDGFRA and CAV1 expression were both significantly more frequent in the NST components of MpBC cases with lymph node metastasis than in the NST components of those without metastasis, supporting the GSEA results." (PMID 36707876, 2023). "Among these genes, PDGFRA and CAV1 expression were significantly more frequent in the NST components of the MpBC cases with lymph node metastasis than in the NST components of those without metastasis, thereby supporting the GSEA results." (PMID 36707876, 2023). "Furthermore, to clarify the role of Cav-1 expression in the patients with lymph node metastasis, we performed univariate and multivariate analyses for RFS and CSS in the subgroup of the patients with lymph node metastasis." (PMID 28828003, 2017).
lymph node metastasis (continued). "Many studies, including a recent meta-analysis, have confirmed that Cav1 tissue expression is a negative prognostic marker in NSCLC and that it is correlated with differentiation, T stage and lymph node metastasis." (PMID 26315660, 2015). "Correlation between lymph node metastasis and expression of CTSB and cav-1 in IBC versus non-IBC patients." (PMID 21199580, 2011).
triple-negative breast carcinoma (21 papers, 2008 to 2026). An invasive breast carcinoma which is negative for expression of estrogen receptor (ER), progesterone receptor (PR), and human epidermal growth factor receptor 2 (HER2). "Caveolin-1 (Cav1) plays a complex role in cancer progression and has been ascribed both tumor promoter and suppressor functions; elevated Cav1 is associated with a poor prognosis in prostate, melanoma cancers and triple negative breast cancer." (PMID 31803361, 2019). "In contrast, triple negative breast cancer patients with a loss of stromal Cav-1 have a five-year survival rate of < 10%." (PMID 21605374, 2011). "Another study investigated the role of Cav-1 in the metastatic potential of murine triple-negative breast cancer cells." (PMID 41439026, 2025). "CCLE database analysis showed that CAV1 and integrin α6β4 were highly expressed in triple-negative breast cancer (TNBC) MDA-MB-231 cells." (PMID 39494337, 2024). "The CAV1/Src/ FAK/ integrin α6β4 signaling regulatory mechanism will also provide a reference for Src inhibitor treatment of triple-negative breast cancer." (PMID 39494337, 2024). "have showed caveolin-1 expression level was a potential indicator for predicting efficacy of docetaxel in the treatment of triple-negative breast cancer." (PMID 34513683, 2021). "In conclusion, our study revealed that SA suppressed triple-negative breast cancer metastasis via blocking late-phase autophagy and highlight a novel role of Cav-1 in autophagic control via suppressing autolysosomal formation." (PMID 33381039, 2020). "Overall, our findings not only indicate that SA acts as a novel late-phase autophagic inhibitor with anti-metastatic activities in triple-negative breast cancer, but also highlight Cav-1 as a regulator in controlling late-phase autophagic activity." (PMID 33381039, 2020). "In light of the evidences reported here we thought that our data offer clues to better explore CAV1 isoforms in tumors, thus providing new opportunities to improve both treatment and prognosis of triple-negative breast cancer." (PMID 32825330, 2020). "More patients with HER2+ and triple-negative breast cancer had low tumor Cav-1 expression (Chi-square test p = 0.006)." (PMID 30348118, 2018). "While the majority of triple-negative breast cancers are basal-like, only 4 triple-negative breast cancers were included in Cav-1 staining analysis in our study and we didn’t test the expression of basal markers concurrently in these patients." (PMID 30348118, 2018). "For example, triple negative breast cancer patients with high stromal Cav-1 have a 12-year survival rate of >75%." (PMID 21605374, 2011). "Similarly, Tubeimoside V sensitizes triple-negative breast cancer MDA-MB-231 cells to anoikis by modulating caveolin-1-related signaling pathways, and disulfiram activates calpain-mediated anoikis, inhibiting lung colonization in triple-negative breast cancer." (PMID 40746552, 2025). "In the present study, we further demonstrated that Cav-1 might act as the main pharmaceutical target of SA in suppressing metastasis on triple-negative breast cancer cell lines." (PMID 33381039, 2020). "Since we have previously shown that caveolins are primarily responsible for the NG intracellular uptake in the triple-negative breast cancer cell line MDA-MB-231, we investigated the expression of Caveolin 1 in the TC cell lines used." (PMID 40006633, 2025). "Therefore, we discovered that the dephosphorylation of Cav-1 can be achieved using pharmacological stimulation of the potassium channel Kv11.1, which is uniquely and highly expressed in MDA-MB-231 triple negative breast cancer cells." (PMID 35954304, 2022). "In triple negative breast cancer (TNBC) patients, the 5-year survival rate is 75.5% for high stromal Cav1 versus 9.4% for absent stromal Cav1." (PMID 37822942, 2023).
triple-negative breast carcinoma (continued). "EGFR nuclear translocation is stimulated by radiation mediated by Cavelolin-1 (CAV-1), and CAV-1 knockdown radiosensitizes triple-negative breast cancer, a tumor type for which there are no current targeted therapies and poor prognoses." (PMID 34337349, 2021).